ACP5 (acid phosphatase 5, tartrate resistant)
Diseases named in the same sentence as ACP5 in open-access papers (continued):
Sharing a sentence is not in itself a finding about the gene and the disease.
depression (1 paper, 2022). "All above results suggest that the increased Acp5 inhibited the pyramidal neurons excitability and contributed to comorbid-like behavior of neuropathic pain and depression induced by SNI in rats." (PMID 35690777, 2022). "To further confirm the role of Acp5 in pyramidal neurons of PrL in the comorbidity of neuropathic pain and depression in rats, we overexpressed the Acp5 by bilateral injection of AAV–DIO–Acp5–EGFP into the PrL together with AAV–CaMKIIa–Cre." (PMID 35690777, 2022). "The results suggest that comorbidity of neuropathic pain/depression-induced by SNI significantly increased the Acp5 level in the PrL neurons." (PMID 35690777, 2022). "Next, we observed the role of p-STAT3 in the Acp5 expression following the acquisition of comorbidity of neuropathic pain and depression." (PMID 35690777, 2022). "Besides, overexpression of Acp5 in pyramidal neurons reduced the number of action potential and induced the mechanical allodynia and depression-like behavior in naïve rats." (PMID 35690777, 2022). "Taken together, the IL6/STAT3/Acp5 pathway modulated the excitability of PrL pyramidal neurons to change the adaption of PrL region, which critically involved in the development of comorbidity of neuropathic pain/depression." (PMID 35690777, 2022). "Therefore, it is hypothesis that the upregulated Acp5 may be a common molecular, via modulated the activity of immune system and nervous system, to contributed to the neuropathic pain and depression-like behavior induced by SNI." (PMID 35690777, 2022).
dysplasia (1 paper, 2017). A usually neoplastic transformation of the cell, associated with altered architectural tissue patterns. "Hypomorphic ACP5 mutations impair endochondral bone growth and create an interferon (INF) signature, which lead to distinctive spondylar and metaphyseal dysplasias, and extraskeletal morbidity, such as neurological involvement and immune dysregulation, respectively." (PMID 28740483, 2017).
fibrosis (1 paper, 2024). the formation of excess fibrous connective tissue in an organ or tissue in a reparative or reactive process. "In conclusion, the inhibition of ACP5 blocks fibroblast activation, reduces cardiac fibrosis in the infarction area, and improves cardiac function." (PMID 38879488, 2024).
lung adenocarcinoma (1 paper, 2019). A carcinoma that arises from the lung and is characterized by the presence of malignant glandular epithelial cells. "It has also demonstrated that overexpression of ACP5 is associated with lung adenocarcinoma progression and may be a potential prognostic biomarker for lung adenocarcinoma." (PMID 30778327, 2019).
monocytic leukemia (1 paper, 2024). "Next, we used macrophages derived from human monocytic leukemia THP-1 cells as an alternative model for macrophages to validate the role of Lyso-Gb-1 in ACP5 expression." (PMID 38667330, 2024).
myelofibrosis (1 paper, 2023). A partial or complete replacement of the bone marrow stroma by fibrous tissue. "The analysis identified a somatic variant in MPL (related to myelofibrosis) and a heterozygous variant in ACP5 (associated with immune dysregulation disorder), both matching the patient’s phenotype." (PMID 38259611, 2023).
Myocardial fibrosis (1 paper, 2024). "In summary, the present data support the involvement of ACP5 in the progression of myocardial fibrosis after MI." (PMID 38879488, 2024). "ACP5 may influence the proliferation, migration, and phenotypic transition of CFs, leading to the development of myocardial fibrosis after MI through modulating the ERK/GSK3β/β-catenin signaling pathway." (PMID 38879488, 2024). "First, ACP5 plays a crucial role in regulating myocardial fibrosis following MI." (PMID 38879488, 2024). "This is the first study to propose that ACP5 may promote myocardial fibrosis after MI through the regulation of the ERK/GSK3β/β-catenin pathway." (PMID 38879488, 2024). "The present results support the hypothesis that ACP5 plays a key role in the pathogenesis of cardiac fibrosis after MI and provide insights into the regulatory mechanisms of myocardial fibrosis." (PMID 38879488, 2024). "Therefore, targeting ACP5 may be a potential therapeutic approach for treating MI and offers new research directions for the treatment of myocardial fibrosis following MI." (PMID 38879488, 2024). "ACP5 influences the proliferation, migration, and phenotypic transition of CFs via modulating the ERK/GSK3β/β-catenin signaling pathway, leading to the development of myocardial fibrosis after MI." (PMID 38879488, 2024).
oral cancer (1 paper, 2025). "Further, we selected genes (ACP5, SPP1, and MMP12) from our study on late-stage oral cancer buccal mucosa patients." (PMID 41410801, 2025).
periodontal diseases (1 paper, 2026). "In periodontal diseases, MMP-9 and IL-6 play roles in inflammatory-driven bone loss, while TNF-α and TRAP (ACP5) are implicated in osteoclast activation." (PMID 41559024, 2026).
rectal cancer (1 paper, 2024). A primary or metastatic malignant neoplasm that affects the rectum. "ACP5 has been shown to correlate with poor patient prognosis in cancers such as gastric and rectal cancers, and to correlate with malignant tumor progression by affecting malignant phenotypes such as cell proliferation and invasion." (PMID 38435998, 2024).
Sleep apnea (1 paper, 2022). An intermittent cessation of airflow at the mouth and nose during sleep is known as sleep apnea. "A novel, potentially robust sleep apnea marker identified in this study is Tartrate-resistant acid phosphatase (TrATPase), also called acid phosphatase 5, tartrate resistant (ACP5)." (PMID 35887329, 2022).
staphylococcus aureus infection (1 paper, 2016). An infectious process in which the bacteria Staphylococcus aureus is present. "The finding of recurrent infection in SPENCD is of interest given the susceptibility to Staphylococcus aureus infection noted in the ACP5 knock-out mouse." (PMID 26951490, 2016).
triple-negative breast carcinoma (1 paper, 2024). An invasive breast carcinoma which is negative for expression of estrogen receptor (ER), progesterone receptor (PR), and human epidermal growth factor receptor 2 (HER2). "Given that ACP5 is a key gene influencing high RiskScore, we inhibited the expression of ACP5 in MDA-MB-468 and MDA-MB-231 cell lines, and by transwell assay, we could observe the ability of ACP5 to promote the proliferation of triple-negative breast cancer cell lines." (PMID 38435998, 2024).
tumor (51 papers, 2006 to 2026). "Immunofluorescence confirmed that ACP5 distribution within the tumor and stroma was more obvious in CRC tissues with high RANK expression than in those with low RANK expression." (PMID 33795653, 2021). "Accordingly, the expression of osteoclast differentiation and function genes Acp5, Ctsk, Mmp9, and Nfatc1 was much higher in the bone of tumor-bearing mice than those in the bone of tumor-free mice." (PMID 33391543, 2021). "The results showed that ACP5 expression was higher in primary tumor samples than in normal samples." (PMID 33753989, 2021). "The tumor also expressed the osteoblast marker Bglap and the osteoclast markers Acp5 and Ctsk." (PMID 33468253, 2021). "Myeloid cells were subclustered into monocyte, Tumor-associated macrophage (TAM) including SPP1+ TAM, C1Qs+TAM, HSPs+ TAM, ACP5+ TAM, and CCL5+ TAM, classical dendritic cell (cDC) encompassing cDC, CD1A+ DC, LAMP3+ DC and PCLAF+ DC, plasmacytoid DC (pDC) as well as unknown subpopulations." (PMID 40904511, 2025). "Among them, the TREM2+ subpopulation was characterized by high expression of GPNMB, TREM2, ACP5, LGMN, and TIMP2, and mainly distributed at the boundary and core region of the tumor." (PMID 38948071, 2024). "ACP5 and ACP6 are unfavourable prognostic genes to tumour growth and immune system evasion, highlighting their role in cancer progression." (PMID 39457550, 2024). "We found potential immunotherapy targets, for example, ACP5 and CCR8 for tumor-infiltrating Tregs and MT1 for CD8+ Tex cells." (PMID 35562760, 2022). "We found potential immunotherapy targets, for example, ACP5, MAGEH1, TNFRSF9 and CCR8 for tumor infiltrating Tregs and MT1 for exhausted CD8+ T cells (CD8+ Tex cells)." (PMID 35562760, 2022). "Among the 18 Treg-specific overlapping genes, ACP5, MAGEH1, TNFRSF9 and CCR8 were exclusively expressed in tumor-infiltrating Tregs and are potential immunotherapy targets for tumor-infiltrating Tregs." (PMID 35562760, 2022). "Correspondingly, serum CTX-1 level and the expression of osteoclast signature genes Acp5, Ctsk, Mmp9, and Nfatc1 in mice bearing SCP28/Sh-miR-21 tumors were comparable with tumor-free mice." (PMID 33391543, 2021). "Moreover, ACP5, MAGEH1, TNFRSF9 and CCR8 were especially populated in tumor-infiltrating Tregs and IKZF2 was only highly expressed in paratumor-infiltrating Tregs." (PMID 35562760, 2022). "Moreover, genes representing mesodermal or/and endodermal tissue differentiation (ACP5, ACTA2, BGLAP, CTSK, DESMIN, FOXA2) were activated in tumor." (PMID 33468253, 2021). "Xenograft tumor of HCT 116 showed an increased expression of neuronal genes MAP2 and SYN1, neural stemness genes CDH2, MSI1, NCAM1, SOX2/9, VIM and ZEB2, and genes for mesodermal and endodermal tissues (ACP5, AFP, DESMIN, HNF4A and KRT8)." (PMID 33468253, 2021).
cancer (26 papers, 2015 to 2026). A tumor composed of atypical neoplastic, often pleomorphic cells that invade other tissues. "The metalloenzyme tartrate-resistant acid phosphatase (TRAP/ACP5) has recently gained prominence due to its association with clinically relevant cancer parameters." (PMID 38067167, 2023). "As the pathways and risk factors are often shared by cancer and IPF31,32, we detected the levels of ACP5 in sera and lung samples from IPF patients." (PMID 35013220, 2022). "Briefly, myeloid cells (LYZ+), lymphocytes (CD3D+), osteoclasts (ACP5+), endothelial cells (CLDN5+), perivascular-like cells (PVL) (RGS5+TAGLNhigh), cancer-associated fibroblasts (CAFs) (TAGLNlowACTA2+) and proliferative cells (MKI67+) were identified in the study." (PMID 36596773, 2023). "ACP5 encodes tartrate-resistant acid phosphatase (TRAP) that is a metalloenzyme expressed in activated osteoclasts and macrophages, which has recently gained traction as a driving factor for metastasis and is significantly associated with cancer progression." (PMID 30778327, 2019). "In breast cancer-related studies, the TRAP/ACP5/uteroferrin/purple acid phosphatase/PP5 signaling axis can act as a driver mediating breast cancer invasion and mediate cancer malignant progression at the cellular level." (PMID 38435998, 2024).
infection (5 papers, 2016 to 2025). The state of being infected such as from the introduction of a foreign agent such as serum, vaccine, antigenic substance or organism. "TRAP-deficient macrophages from Acp5-null mice demonstrate an altered cytokine profile and a decreased ability to clear bacteria after infection." (PMID 41049574, 2025).
skeletal dysplasia (5 papers, 2017 to 2026). Any Mendelian diseases that affects growth and development of the skeleton. "More specifically, these include skeletal dysplasia and radiolucent metaphysical lesions which arise from biallelic mutations of ACP5 gene, which encodes TRACP enzyme." (PMID 32214327, 2020). "SLE-like features are also seen in spondyloenchondrodysplasia (SPENCD), a skeletal dysplasia caused by biallelic mutations in ACP5, which encodes tartrate-resistant acid phosphatase (TRAP)." (PMID 39264482, 2024).
bone disorder (4 papers, 2012 to 2025). "TRAP, encoded by the Acp5 gene, is a well-established marker of osteoclast activity and has been implicated in various bone disorders, including spondyloenchondrodysplasia." (PMID 40114968, 2025). "Pathway analysis showed that ACP5 and its interacting genes are associated with osteoclast differentiation, associated with bone disorders in SPENCD." (PMID 35633950, 2022).
cardiovascular disease (2 papers, 2017 to 2024). "However, the role of ACP5 in cardiovascular diseases remains unclear." (PMID 38879488, 2024).
hematological malignancies (1 paper, 2022). "Indeed, ACP5 is associated with skeletal disorders and other diseases such as neoplastic disorders, including hematological malignancies." (PMID 35633950, 2022).
infectious disease (1 paper, 2023). A disorder directly resulting from the presence and activity of a microbial, viral, or parasitic agent in humans. "Conversely, the remaining three genes carrying homozygous missense variants in the twins–SLC17A9, ZNF678 and ACP5 –had no known link to infectious diseases." (PMID 36972292, 2023).
vasculopathy (1 paper, 2022). "Mutations in ACP5 and SAMHD1 are known to drive the pathogenesis of SPENCD and AGS, both of which are monogenic interferon diseases characterized by increased type I IFN signaling leading to vasculopathy, autoinflammation, and SLE-like disease." (PMID 35633950, 2022).
ACP5 also shares sentences with these, for which no sentence is quoted: bone metastasis (8 papers); diabetes (8); Osteopenia (6); Hypocalcemia (5); glioma (4); multiple myeloma (4); type 2 diabetes mellitus (4); hairy cell leukemia (3); schizophrenia (3); anemia (2); ankylosis (2); autoimmune disease (2); bone tumors (2); chronic apical periodontitis (2); haemophilia (2); Hypercalciuria (2); hyperlipidemia (2); Hypertension (2); Insulin resistance (2); malnutrition (2); neurological disease (2); osteoarthritis (2); renal failure (2); secondary hyperparathyroidism (2); type 1 diabetes (2); viral infection (2); abscesses (1); acute myeloblastic leukemia (1); Alzheimer disease (1); aneurysm (1).
A further 72 diseases each share a sentence with ACP5 in 1 paper.